GSDMC (gasdermin C)
Description:
[Gasdermin-C]: This form constitutes the precursor of the pore-forming protein: upon cleavage, the released N-terminal moiety (Gasdermin-C, N-terminal) binds to membranes and forms pores, triggering pyroptosis. [Gasdermin-C, N-terminal]: Pore-forming protein that causes membrane permeabilization and pyroptosis. Produced by the cleavage of gasdermin-C by caspase CASP8 in response to death signals. After cleavage, moves to the plasma membrane where it strongly binds to membrane inner leaflet lipids. Homooligomerizes within the membrane and forms pores of 10-15 nanometers (nm) of inner diameter, triggering pyroptosis.
Synonyms: MLZE
Tractability: Antibody: UniProt places it where antibodies can reach, with high confidence; its Gene Ontology location is reachable by antibodies, with high confidence.
Gene: Protein-coding gene on chromosome 8 (129,748,196 to 129,786,624, reverse strand). Ensembl gene ENSG00000147697.
Subcellular location: Cytoplasm, cytosol (Gasdermin-C); Cell membrane (Gasdermin-C, N-terminal)
Subcellular location (Human Protein Atlas): Vesicles
Gene Ontology:
Molecular function: phosphatidylinositol-4,5-bisphosphate binding; phosphatidylinositol-4-phosphate binding; phosphatidylserine binding
Biological process: defense response to bacterium; pyroptotic inflammatory response
Cellular component: cytoplasm; plasma membrane; cytosol
Genetic constraint (gnomAD): Loss-of-function variants: 39 observed, 44.29 expected, observed/expected ratio (o/e) 0.88, 90% interval 0.68 to 1.15. The upper end of that interval is the gene's LOEUF score, 1.15, which puts it in group 5 of 6, group 1 being the genes least tolerant of losing a copy. Missense variants: 564 observed, 532.7 expected, observed/expected ratio (o/e) 1.06, 90% interval 0.99 to 1.13. Synonymous variants: 213 observed, 200.1 expected, observed/expected ratio (o/e) 1.06, 90% interval 0.95 to 1.19.
Homologues: Orthologues: chimpanzee GSDMC (99% identical), macaque GSDMC (92% identical), dog GSDMC (53% identical), pig GSDMC (50% identical), rat Gsdmc (46% identical), mouse Gsdmc (44% identical), mouse Gsdmc2 (44% identical), mouse Gsdmc3 (44% identical), mouse Gsdmc4 (43% identical), zebrafish pjvk (13% identical). Paralogues in human: GSDMA (27% identical), GSDMD (27% identical), GSDMB (18% identical), PJVK (12% identical).
Diseases named in the same sentence as GSDMC in open-access papers:
GSDMC is named in the same sentence as 67 diseases in open-access papers, as found by Europe PMC text mining. Sharing a sentence is not in itself a finding about the gene and the disease. The quoted sentences say what the papers report.
breast cancer (43 papers, 2016 to 2025). A primary or metastatic malignant neoplasm involving the breast. "GSDMC is up-regulated and proved to be associated with poor prognosis both in breast cancer and lung adenocarcinoma, which is consistent with the manifestations in our constructed model." (PMID 37950289, 2023). "In breast cancer, caspase-8-mediated pyroptosis was caused by upregulation of the expression of gasdermin C (GSDMC)." (PMID 34869771, 2021). "Antibiotics such as doxorubicin could upregulate the expression of PD-L1 and GSDMC, and activate caspase-8, and then cause a pyroptotic death in breast cancer cells." (PMID 40064873, 2025). "In this concern, programmed death-ligand 1 (PD-L1) translocates to the nucleus of hypoxic cells and upregulates the expression of an important mediator of pyroptosis, Gasdermin C (GSDMC), which is associated with a poor probability of overall survival in breast cancer (BC)." (PMID 38994937, 2024). "Moreover, overexpression of GSDMC is associated with poorer survival in breast cancer, which is consistent with our findings." (PMID 36196256, 2022). "In MDA-MB-231 breast cancer cells, high expression of GSDMC/caspase-8 via TNF-α inducing, is correlated with poor survival." (PMID 41291696, 2025). "Another study showed the expression levels of GSDMC in breast cancer cells are significantly upregulated compared to normal breast cells (MCF10A)." (PMID 41291696, 2025). "Although the cleavage of GSDMC by Caspase‐8 was reported in breast cancer, conditional deletion of Caspase‐8 in intestinal epithelial cells dramatically enhanced GSDMC activation rather than inhibiting it, likely due to increased Caspase‐6 activity." (PMID 40213993, 2025). "As a key gene regulating pyroptosis, GSDMC sensitizes breast cancer cells to poly(ADP-ribose) polymerase inhibitors and induces activation of anti-cancer immune-related biological processes." (PMID 39834939, 2024). "Prompted by reported correlations between GSDMC expression and immune parameters in breast cancer, we focused our investigation on the role of GSDMC in fully immunocompetent PDAC models." (PMID 39297408, 2024). "TNF-α-induced GSDMC cleavage at Asp365, unleashing the GSDMC-NT to form pores and initiate cell pyroptosis in breast cancer cells." (PMID 35795683, 2022). "Under hypoxia, p-STAT3 interacts with PD-L1 to promote its nuclear translocation and enhances gasdermin C (GSDMC) transcription, thereby inducing pyroptosis in breast cancer (BC) cells." (PMID 35907881, 2022). "Upregulated GSDMC also refers to poor clinical outcomes for lung cancer, breast cancer, and melanoma, similar to our findings in HCC." (PMID 35535333, 2022). "It showed a low mRNA expression trend of GPX4, GSDMD and GSDMC in all three types of breast cancer cells, while the mRNA expression of IL18 varied." (PMID 36138348, 2022). "Among them, IL-18 [p = 0.015, HR(95%CI): 0.832(0.717–0.965)] was a protective factor as well as GSDMC [p = 0.044, HR(95%CI): 1.120(1.003–1.251)] and TIRAP [p = 0.025, HR(95%CI): 1.336(1.037–1.722)] were risk factors for breast cancer prognoses." (PMID 34589498, 2021). "As shown in univariate cox regression analyses, IL-18, GSDMC, and TIRAP were significantly associated with survival outcomes of breast cancer." (PMID 34589498, 2021). "Our univariate cox regression analyses showed that IL-18 was a protective factor as well as GSDMC and TIRAP were risk factors for breast cancer prognoses." (PMID 34589498, 2021). "A three-gene regression model including IL18, GSDMC, and TIRAP was regarded as an independent risk factor of breast cancer prognoses." (PMID 34589498, 2021). "Furthermore, pyroptosis has been linked to poor patient outcomes, such as in cases where caspase-8/GSDMC-mediated pyroptosis correlates with adverse prognoses in breast cancer patients." (PMID 39221221, 2024).
breast cancer (continued). "Mechanistically, p-Stat3 could physically bind with nuclear-translocated PD-L1 and its complexation interacts with the site of the GSDMC promoter, enhancing GSDMC expression transcriptionally in breast cancer cells." (PMID 36823153, 2023). "Thus, these drugs exhibit anti-tumor activity, probably through strong inflammatory responses in PD-L1+ or GSDMC+ breast cancers." (PMID 38016064, 2023). "Interestingly, tumor necrosis factor (TNF)-mediated apoptosis is converted into pyroptosis with the expression of gasdermin C (GSDMC) mediated by programmed cell death ligand 1 (PD-L1) in breast cancer." (PMID 36209102, 2022). "For example, while the upregulation of GSDMC is cleaved by caspase-8 and induces pyroptosis in MDA-MB-231 and BT549 breast cancer cells, knockdown of GSDMC significantly inhibits proliferation and tumorigenesis in colorectal cancer in a pyroptosis-independent manner." (PMID 35990696, 2022). "In this study, we investigated the role and mechanism of GSDMC in breast cancer." (PMID 36042287, 2022). "A recent study on the role of NPD-L1 and TNFα in breast cancer showed that under hypoxia, PD-L1 can migrate to the nucleus and activate GSDMC, which is then cleaved by the TNFα activated-caspase-8, triggering pyroptosis and promoting the death of breast cancer cells." (PMID 35359956, 2022). "Also, GSDMC is linked to metastasis in malignant melanoma, and the high expression of GSDMC is related to the poor survival of breast cancer." (PMID 34459122, 2021). "Furthermore, CASP8 (2%), NLRC4 (1%), NLRP3 (1%), NLRP2 (1%), PLCG1 (1%), NLRP1 (1%), NLRP7 (1%), SCAF11 (1%), GSDMC (1%), and NOD1 (1%) occurred somatic mutations as well as most of them had high frequencies of CNV in breast cancer." (PMID 34589498, 2021). "Furthermore, it is reported that antibiotic chemotherapy drugs also induce caspase‐8/GSDMC‐mediated pyroptosis in breast cancer." (PMID 34459122, 2021). "GSDMC was then cleaved by caspase-8 in breast cancer cells treated with TNF-α." (PMID 33634141, 2021). "Thus, our data revealed a new mechanism of GSDMC activation by Caspase‐6 to induce colon cancer cell pyroptosis under Hypoxia and low‐glucose conditions, which was different from Caspase‐8 mediated GSDMC activation in breast cancer." (PMID 40213993, 2025). "Additionally, chemo-antibiotic drugs like daunorubicin, actinomycin D, doxorubicin (DOX), and epirubicin were found to increase the expression of GSDMC and nuclear PD-L1 in breast cancer, which further promoted caspase-3/8-mediated pathway and ultimately led to pyroptosis." (PMID 36209102, 2022). "In a recent study, chromosomal engineering in mice showed that copy number gains in the Myc gene promote tumorigenesis in mammary tumors only if the downstream sequence encompassing Pvt1, Ccdc26, and Gsdmc is also amplified, suggesting that GSDMC may play a role in tumor progression." (PMID 27835699, 2016). "Ultimately, caspase-8 cleaves GSDMC to generate GSDMC-NTD, inducing pyroptosis in breast cancer cells." (PMID 37781519, 2023). "The presence of programmed death ligand 1 (PD-L1), macrophage-derived TNF-α, antibiotics, or chemotherapy can induce pyroptosis by the caspase-8/GSDMC pathway, and TNF-α can induce pyroptosis through GSDMC in MDA-MB-231 breast cancer cells." (PMID 36605484, 2023). "As shown, compared with MCF-10A, the expression levels of GSDMC, GZMB and IL18 were upregulated, while TP63 was found with lower expression level in breast cancer cells SK-BR-3, BT-549, MCF-7, and MDA-MB-231 (P < 0.05)." (PMID 36936274, 2022). "Compared with a human mammary epithelial cell line MCF-10A, the expression levels of GSDMC, GZMB and IL18 were upregulated, while TP63 was found with lower expression level in breast cancer cells SK-BR-3, BT-549, MCF-7, and MDA-MB-231 using RT-qPCR assay." (PMID 36936274, 2022). "The results showed the expression and distribution of GPX4, GSDMD, GSDMC, IL18 in breast cancer and normal tissues." (PMID 36138348, 2022).
breast cancer (continued). "As depicted in western blotting, IL-18, GSDMC, and TIRAP expression was all markedly up-regulated in breast cancer cells MDA-MB-231 and HCC70 compared with normal breast cells MCF-10A." (PMID 34589498, 2021). "This set comprised senescence markers (CDKN1A, LMNB1, MKI67), apoptosis regulators (BCL2, BCL2L1), a highly overexpressed gene (ITGB6), and drug targets (ACTA2, GSDMC, KRT6A, PDE1A, PSMA8), all of which showed strong concordance with our RNA-seq data in all four breast cancer cell lines." (PMID 40312750, 2025). "In contrast, for BRCA2-mut breast cancer, B3GNT7, CTSV, and GSDMC were the most significant." (PMID 40647506, 2025). "For instance, upregulation of GSDMD in lung cancer or GSDMC in colorectal cancer correlates with poor prognosis and therapeutic resistance, whereas reactivation of GSDME in breast cancer or AIM2 in gastric cancer has been shown to re-sensitize tumors to chemotherapy and inhibit proliferation." (PMID 41291696, 2025). "GSDMB, GSDMC, and GSDME have been reported as potential prognostic markers for breast cancer." (PMID 40064873, 2025). "Researchers found that gasdermin C (GSDMC) was transcriptionally regulated by PD-L1 in the nucleus under the condition of hypoxia, and further eliminated by TAM-derived caspase-8, which in turn induced pyroptosis in breast cancer cells." (PMID 36707884, 2023). "Virtually all chemotherapy medicines can induce PD-L1 translocation and upregulation of GSDMC, whereas only the antibiotics such as doxorubicin, epirubicin, daunorubicin, and actinomycin D can activate caspase-8, induce GSDMC cleavage, and induce pyroptosis in MDA-MB-231 breast cancer cells." (PMID 38016064, 2023). "Several studies have shown that the pyroptosis core genes behave differently in different tumors, with GSDMC, GSDMD, and GSDMB acting as oncogenes in colorectal cancer, small-cell lung cancer, and breast cancer, respectively, while GSDME acts as a tumor suppressor in a variety of cancers." (PMID 35769504, 2022). "At the same time, they also found that some chemotherapeutics such as daunorubicin, doxorubicin, epirubicin and actinomycin D could induce the expression of nPD-L1 (nuclear PD-L1) and GSDMC as well as the activation of caspase-8, inducing pyroptosis in MDA-MB-231 human breast cancer cells." (PMID 34381721, 2021). "Therefore, caspase-8/GSDMC initiated a non-canonical pyroptosis pathway in breast cancer cells." (PMID 33634141, 2021).
melanoma (31 papers, 2012 to 2026). A malignant, usually aggressive tumor composed of atypical, neoplastic melanocytes. "Hypoxia-associated gene risk signature, which including GSDMC, also show satisfactory prognostic effects in melanoma." (PMID 34721986, 2021). "GSDMC is barely expressed in normal epithelial cells, but upregulated in malignant melanoma, which may be associated with melanoma invasion and metastasis." (PMID 35896522, 2022). "In particular, we found that melanoma patients with high expression of PLAU or GSDMC had better prognosis when treated with PD-1 inhibitors (nivolumab and pembrolizumab)." (PMID 41584044, 2026). "Here, we discovered a chemical compound, dodecyl 1H-benzo[d]imidazole-5-carboxylate (DdBIC), that targeted the nuclear receptor Nur77 to induce pyroptosis through cleaving GSDMC by granzyme B in melanoma cells." (PMID 41407678, 2025). "Here, a chemical compound, dodecyl 1H-benzo[d]imidazole-5-carboxylate (DdBIC), designed by our group, was shown to effectively induce GSDMC-dependent pyroptosis in melanoma cells." (PMID 41407678, 2025). "GSDMC, initially cloned from metastatic melanoma cells, has been demonstrated as a potential executioner of pyroptosis." (PMID 41407678, 2025). "Initially, abnormal up-regulation of GSDMC is identified in metastatic melanoma, earning it the label of melanoma-derived leucine zipper extra-nuclear factor (MLZE) and making it a molecular beacon for tracking melanoma evolution." (PMID 38304430, 2024). "GSDMC was originally found to be highly expressed in metastatic melanoma cells and was first known as a melanoma-derived leucine zipper-containing extranuclear factor (MLZE)." (PMID 39062587, 2024). "In melanoma cells, the metabolite α-ketoglutarate (α-KG), known to induce pyroptosis through GSDMC, inhibits tumor progression and metastasis." (PMID 38066523, 2023). "Initially identified in metastatic melanoma cells, GSDMC was named melanoma-derived leucine zipper-containing extranuclear factor (MLZE)." (PMID 38066523, 2023). "The expression of GSDMC is restricted to the esophagus, skin, spleen and vagina and its expression was first used as a marker for melanoma progression." (PMID 35795683, 2022). "GSDMC, also known as melanoma-derived leucine zipper containing extranuclear factor, was named by its initial observation in melanoma metastases in mice." (PMID 35795683, 2022). "When GSDMC was discovered in metastatic melanoma cells, it was named melanoma-derived leucine zipper extranuclear factor (MLZE) due to a suspected leucine zipper in its C-terminal domain." (PMID 35677632, 2022). "GSDMC, also called melanoma-derived leucine zipper extranuclear factor (MLZE), was first described from melanoma cells." (PMID 35535333, 2022). "At first, GSDMC shows high expression within metastatic melanoma cells, so it is consequently called melanoma-derived leucine zipper-containing extranuclear factor (MLZE)." (PMID 36552744, 2022). "Researchers defined GSDMC as a marker of melanoma occurrence, and GSDMC is expressed in a number of cells and tissues, and is also one of the star molecules." (PMID 35647057, 2022). "With the further study, researchers found that the expression of GSDMC in melanoma cells has been at a high level." (PMID 35647057, 2022). "MLZE (GSDMC) as a novel gene was first isolated whose expression in accordance with metastatic ability of melanoma cells." (PMID 34459122, 2021). "GSDMC was initially discovered to be highly expressed in metastatic melanoma cells and was referred to as melanoma-derived leucine zipper-containing extranuclear factor (MLZE)." (PMID 33634141, 2021). "GSDMC, also known as melanoma-derived leucine zipper-containing extranuclear factor, was named after metastatic mice melanoma cells in which its increased expression was observed and the gene was first identified." (PMID 34858408, 2021). "The expression levels of mouse GSDMC were positively correlated with the metastatic ability of B16 melanoma cell lines." (PMID 34858408, 2021).